LRP5 (LDL receptor related protein 5)
Diseases named in the same sentence as LRP5 in open-access papers (continued):
Sharing a sentence is not in itself a finding about the gene and the disease.
tumor (continued). "In addition, the overexpression of Lrp5 elevated Snail, MMP9, Runx2, and TGFβ and promoted the proliferation and invasion of 4T1Br tumor cells." (PMID 34031366, 2021). "In evaluating the Lrp5-mediated and Lrp5-non-mediated mechanisms of loading-driven tumor suppression, we examined the expression of oncogenic genes such as Runx2, Snail, and TGFβ in the context of Lrp5 overexpression and silencing." (PMID 33450808, 2021). "We observed that CM from human osteocytes either with or without Lrp5 overexpression also inhibited the proliferation, invasion, and migration of tumor cells." (PMID 34230453, 2021). "Collectively, the result supported the possibility that knee loading suppressed tumor progression in part by systematically elevating dopamine and chemerin, while reducing cholesterol and nexin, even in the absence of Lrp5 in osteocytes." (PMID 33450808, 2021). "Considering these results collectively, we postulate that Lrp5 but not Lrp6 in osteocytes can enhance tumor suppression." (PMID 34230453, 2021). "Knee loading reduced the tumor size and weight in the mammary fat pad in mice regardless of Lrp5 deletion." (PMID 33450808, 2021). "This study revealed that Lrp5 in osteocytes is beneficial to reduce tumor growth in the bone, but loading-driven suppression of tumor growth can take place even in the absence of Lrp5 in osteocytes via the regulation of dopamine and cholesterol." (PMID 33450808, 2021). "Accordingly, tumor DCs lacking LRP5/6 or β-catenin isolated from knockout mouse models displayed increased activation with upregulated expression of co-stimulatory molecule and decreased expression of co-inhibitory molecules (PD-L1, PD-L2)." (PMID 32132993, 2020). "Mechanistically, tumor cells secrete DKK2 that binds its receptor LRP5 inducing interactions between the intracellular domain of LRP5 and STAT5; while STAT5-phosphorylation was not precluded, STAT5 nuclear localization was impeded in cytotoxic cells." (PMID 31766350, 2019). "In agreement, targeting Lrp5/6 expression in WT-CAFs, attenuated β-catenin and YAP activation and diminished their tumour-promoting activities." (PMID 30631061, 2019). "Knocking down endogenous LRP5/6 promoted otherwise nonmetastatic tumor cells to disseminate throughout the body." (PMID 28418856, 2017). "Inactivation of LRP5 resulted in mesenchymal to epithelial shift, lack of translocation of β-catenin to cell surface, increased tumor cell proliferation, decreased colony formation, migration and invasion in vitro." (PMID 24403228, 2013). "In this study, we show that tumor-initiating cells are enriched in the Lrp5-positive fraction, regardless of other phenotypes." (PMID 21541292, 2011). "Tumor onset is dramatically delayed in MMTV-Wnt1;Lrp5−/− and MMTV-Wnt1;Lrp5+/− females." (PMID 19503830, 2009). "Previous data has shown that the absence of Lrp5 confers resistance to Wnt1-induced tumor development." (PMID 19672307, 2009). "The anti-tumor effect of LRP5-overexpressing osteocyte-derived CM was attenuated upon MYO5B knockdown, and functional rescue experiments further confirmed that the integrity of the LIMA1-MYO5B axis is essential for the anti-tumor activity of LRP5-overexpressing osteocyte-derived CM." (PMID 41596426, 2026). "Additionally, cell-cell communication analysis revealed that in chemotherapy-resistant patients, STAR + cells interact with tumor cells through Wnt signaling, specifically via ligand-receptor pairs such as WNT7A-FZD6/FZD3-LRP6/LRP5, components of the canonical Wnt pathway." (PMID 40098624, 2025).
tumor (continued). "Indeed, the activation of EGFR produces the detachment by SRC-mediated phosphorylation of the p120/E-CAD complex from the low-density lipoprotein receptor-related protein 5/6 (LRP5/6), which together with the frizzled receptors (FZD), activates the Wnt signalosome favoring the tumor cell growth." (PMID 35267574, 2022). "However, the expression pattern and role of LRP5 in different tumour microenvironment are not always consistent." (PMID 34997691, 2022). "In addition to tumor suppression the results showed that MSC CMs markedly inhibited the development of RANKL-stimulated RAW264.7 pre-osteoclasts by the overexpression of Akt, Lrp5, β-catenin and Snail." (PMID 33859739, 2021). "Notably, the overexpression of Lrp5 in brain-residing astrocytes did not exert the tumor-suppressing capability, and, to the contrary, it transformed them into tumor-promoting agents." (PMID 33802279, 2021). "Also, Hematoxylin and Eosin (H&E)-stained sagittal sections revealed that knee loading reduced the area of tumor invasion regardless of the deletion of Lrp5 in osteocytes." (PMID 33450808, 2021). "Importantly, the partial silencing of CD44 in EO771 tumor cells reduced the inhibitory effect of recombinant Eno1 proteins on the MTT-based viability, and partially suppressed the Eno1-driven downregulation of Lrp5, Runx2, and TGFβ in EO771 tumor cells." (PMID 34830748, 2021). "Recently, it was proposed that while LRP5/6 and Fz are oncogenic in nature, through direct binding (Fz and LRP5/6) they are able to prevent Fz-regulated non-canonical pathway activation and the non-canonical mediated tumor metastasis." (PMID 28418856, 2017). "The fact that basal cells re-appear suggests instead that the post-transcriptional induction of Lrp5 may not be sufficient to maintain robust tumor growth." (PMID 21541292, 2011). "In addition to the recombinant Eno1 proteins, the partial silencing of CD44 in EO771 tumor cells reduced the inhibitory effect of recombinant Hsp90ab1 proteins on MTT-based viability, and partially suppressed the Hsp90ab1-driven downregulation of Lrp5, Runx2, and TGFβ in EO771 tumor cells." (PMID 34830748, 2021). "They found that under conditions of reduced LRP5/LRP6, Wnt5a strongly activates the non-canonical pathway, leading to elevated p-c-jun and promoting tumor cell metastasis." (PMID 38706907, 2024). "The result showed that the inhibitory effect of Lrp5 CM, Hsp90ab1, and MSN was largely selective to tumor cells than non-tumor cells." (PMID 34976221, 2022). "Surprisingly, another study revealed that FZDs-LRP5/6 interaction can block activation of FZD-mediated non-canonical pathway, further preventing tumor metastasis." (PMID 33618713, 2021). "Of note, the correlation between the WNT2/LRP5/LRP6 signature and the mesenchymal signature was decreased when using STAD tumor data, compared to the non-canonical signatures." (PMID 33869179, 2021). "By positioning LRP5/LIMA1/MYO5B as a functional axis linking osteocytes to tumor cells, we provide a mechanistic framework in which osteocytes are not passive bystanders but active organizers of local anti-tumor responses in bone." (PMID 41596426, 2026). "Furthermore, lower ZFP36 protein level and higher protein levels of LRP5, β-catenin, NANOG were observed in 5 tumor tissues rather than adjacent normal tissues." (PMID 40038255, 2025). "Notably, the inhibitory effect of Lrp5- and Akt-overexpressing MSC CMs, Hsp90ab1 and Calr presented selective inhibition to tumor cells than non-tumor cells." (PMID 33859739, 2021). "The association analyses between NHERF1 and the other markers revealed a positive direct relation between cNHERF1 and FZD4, LRP5, LRP6, and TCF1 expression, but not with β-catenin, suggesting a possible novel tumor progression mechanism, that involves Wnt signaling components." (PMID 31336689, 2019).
tumor (continued). "Co-receptor LRP5 and LRP6 could interplay between themselves and attach to FZD and Wnt ligands, prohibiting FZD mediated canonical and non-canonical pathways and further regulating tumor metastasis." (PMID 29108281, 2017).
cancer (58 papers, 2011 to 2026). A tumor composed of atypical neoplastic, often pleomorphic cells that invade other tissues. "Collectively, these results demonstrate that the elevation in ZFP36 caused by butyrate destabilizes LRP5 mRNA to suppress β-catenin activation, thereby suppressing cancer stem-like traits." (PMID 40038255, 2025). "Furthermore, Wnt pathway activation to increase bone formation has been associated with the risk of cancer, raising concerns about the safety of LRP5 activation therapy." (PMID 40940800, 2025). "Thus, components of the canonical pathway, including LRP5/6, are commonly implicated in cancer progression as oncogenes." (PMID 38706907, 2024). "In addition to LRP6, co-receptor LRP5 was also found to be implicated in Wnt/β-catenin pathway in cancers." (PMID 22570728, 2012). "LRP5, a co-receptor for Wnt ligands, is indispensable for Wnt signal transduction and contributes to cancer progression through pathways such as Wnt/β-catenin." (PMID 41596426, 2026). "Collectively, these new data uncover a novel mechanism by which butyrate regulates LRP5 mRNA decay and cancer stemness." (PMID 40038255, 2025). "The cancer-promoting properties of LRP5 are primarily Wnt signaling activation and alteration of the ATP supply through aerobic glycolysis." (PMID 40940800, 2025). "As such, investigating the molecular mechanism of butyrate regulating this newly defined LRP5 target will provide a theoretical foundation and novel therapeutic strategies aimed at removing cancer stem cells." (PMID 40038255, 2025). "Increased ZFP36 further binding to AU-rich elements in 3’-untranslational region of LRP5 transcript to accelerate the mRNA decay of LRP5, thereby suppressing the activation of Wnt/β-catenin signaling-mediated enhancement of cancer stem-like traits." (PMID 40038255, 2025). "Research has reported that LRP5 plays a role in regulating the prognosis of multiple cancers, including NSCLC." (PMID 39159001, 2024). "Overall, in cancer cells, Wnt ligands bind with members of the Frizzled (Fz) family of serpentine receptors, as well as the LRP5 or LRP6 coreceptors to activate and recruit the phosphoprotein Dishevelled (DSH)." (PMID 34344421, 2021). "Although further studies need to be carried out, these results collectively demonstrated that the role of LRP5 is essential in Hsp90ab1-mediated cancer metastasis." (PMID 30305727, 2019). "Can berberine effectively target LRP5/6 and Frizzled receptors in other cancers to also efficiently inhibit cancer proliferation?" (PMID 30987378, 2019). "Cell surface Wnt receptors in canonical Wnt signaling pathway, including Frizzled (Fzd) family members and LRP5/6, play an important role in cancer progression, especially in maintaining metastatic and self-renewal potential." (PMID 29335534, 2018). "In cancer cells, the binding of Wnt ligands to the Frizzled (Fz) receptor and the low density lipoprotein receptor-related protein 5/6 (LRP5/6) co-receptor on the plasma membrane triggers the disassembly of the destruction complex." (PMID 29784906, 2018). "Besides its role in cancer biology Wnt signaling has gained great medical interest due to its involvement in bone homeostasis, initially discovered through gain- or loss-of-function mutations in the Wnt co-receptor LRP5 leading to either a high-bone mass phenotype or low bone density." (PMID 24312339, 2013). "Together, our results suggest that Mesd C-terminal region constitutes the major LRP5/6-binding domain, and that Mesd protein and its C-terminal region peptide have a potential therapeutic value in cancer." (PMID 23469146, 2013). "Furthermore, we uncover a novel mechanism of butyrate attenuating cancer stemness by accelerating LRP5 mRNA decay via ZFP36." (PMID 40038255, 2025). "In addition, two drugs were identified via bioinformatic tools (Parthenolide and Vorinostat) and repurposed to target LRP5 expression in some cancer cell lines." (PMID 40940800, 2025).
cancer (continued). "Further work should explore the extent to which EGFR and WNT receptors (Frizzled and LRP5/6) each transmit the effect of ZNRF3/RNF43 deactivation at different cancer stages and investigate the efficacy of blocking both EGFR and WNT signaling in treatment of ZNRF3/RNF43-deactivated tumors." (PMID 38260423, 2024). "Several studies have illustrated LRP5 is essential for the activation of canonical Wnt/β‐catenin signalling pathway and gives rise to the malignant transformation of normal cells and excessive proliferation of cancer cells." (PMID 34997691, 2022). "Furthermore, Lrp5-overexpressing osteocyte-derived CM significantly inhibited the ex vivo growth of cancer tissue fragments." (PMID 34230453, 2021). "Due to the critical role of LRP5 in maintaining the integrity of the NPC, thereby promoting cellular proliferation, LRP5 may be involved in promoting cancer progression in HCC." (PMID 31881970, 2019). "Consequently, targeting canonical Wnt receptors such as LRP5/6 holds great promise for treatment of such cancer subsets." (PMID 30664649, 2019). "We examined the effects of LRP5 mRNA expression on patient survival in six cancers." (PMID 29088295, 2017). "In fact, both LRP5 and 6 have been suggested to be oncogenic proteins and could be a target for cancer therapy." (PMID 22570728, 2012). "Also of interest is the recovery of the LRP5 gene, a low-density lipoprotein receptor-related protein that has been identified as potentially oncogenic and part of the cancer-drug-targeted Wnt/beta-catenin signaling pathway." (PMID 22384401, 2012). "Furthermore, MTT assay and CCK8 assay were performed to determine the effects of LRP5/6 knockdown on cancer cell viability and proliferation, which showed that knockdown with LRP5, but not LRP6 or β-catenin, significantly inhibited the cell viability and proliferation of HepG2 cells." (PMID 31881970, 2019). "Therefore, we investigated whether LRP5 overexpression could also play a role in preventing proliferation of adhered cancer cells." (PMID 24266894, 2014). "Overexpression of LRP5 enhances the expression and activation of β-catenin and AKT in aggressive cancers." (PMID 40713830, 2025). "Key components like LRP5 act as co-receptors, transmitting WNT signals and facilitating oncogenic processes across various cancers 16-18." (PMID 38706907, 2024). "The dual-targeted IONPs efficiently bond to both LRP5/6 and uPAR, resulting in inhibition of the Wnt/β-catenin signaling and the CSC-like phenotype of cancer cells as validated by a noticeable reduction in the expressions of LRP5/6, CD44, and uPAR." (PMID 37720349, 2023). "Little is known about the cancer tissue expression of FZD4, LRP5, LRP6 proteins, and we assessed their behavior for the first time in a clinical BC cohort." (PMID 31336689, 2019). "Taken together, our results demonstrated that LRP5 bound to and modulated the stability of NUP37, thereby maintaining the dynamic integrity of NPCs and subsequently promoting cancer progression in HCC." (PMID 31881970, 2019). "This is the first study which examined the physical and functional interaction between LRP5 and NUP37 in cancer." (PMID 31881970, 2019). "For example, genes with Motif 1 in Molecular Mechanisms of Cancer pathway include MAPK1, BRAF, SMAD2, FZD5, FZD8, NOTCH1 and LRP1, whereas genes with Motif 2 and/or Motif3 in the same pathway include LRP5, LRP6, MDM2, CTNND1, SMAD3, SMAD4 and SMAD7." (PMID 26040697, 2015). "Of these exclusively expressed proteins, only 2 (WASL and LRP5) are involved in metastatic processes and none were reported to be involved in specific tissue-targeted cell homing or organotropic cancer metastasis." (PMID 40410902, 2025). "Fifty of fusion genes have been reported and 14 involving known cancer genes (ALDH2-ACAD10, BIRC6-SPAST, BIRC6-TTC27, CGNL1-TCF12, CPEB3-IDE, CTNNA1-KDM3B, DNAJB1-PRKACA, LRP5-CHKA, PPFIBP1-STK38L, RNF213-SLC26A11, RXRA-WDR5, SEC16A-NOTCH1, WNK1-ERC1, and ACVR1B-ACVRL1)." (PMID 37403120, 2023).
cancer (continued). "In contradiction to this finding, another study reported that LRP5 was overexpressed in triple‐negative breast cancers and LRP5 depletion decreased tumorigenesis and induced the apoptosis of cancer cells." (PMID 34997691, 2022). "As ECM-CAFs originate from resident liver fibroblasts, it is interesting to note that in hepatocytes, Wnt/β-catenin signaling can synergize with insulin signaling through IGF1R, LRP5, and LRP6 34, which were concomitantly enriched in ECM-CAF-cancer cell LR interactions." (PMID 36438498, 2022). "We then analysed the highly proliferative cancer cells PC3 and U87MG to test if LRP5 overexpression could inhibit their proliferation." (PMID 24266894, 2014).
bone disorder (8 papers, 2009 to 2025). "In view of these recent studies, the presence of genetic variants, such as the LRP5 mutation with monogenic bone disorder, must be considered as a contributing factor to AFFs, as well as BPs." (PMID 40821177, 2025). "The function of LRP5 in bone development, however, is indisputable; mutations in LRP5 cause various bone disorders and polymorphisms are associated with BMD and bone mineral content in general, but also with reduced BMD and fractures." (PMID 20961463, 2010). "Worth noting however, is we did not observe very highly significant (P < 0.001) association of VDR and LRP5 with body conformation, FL soundness traits and overall leg action, even though these two had been considered as important candidate genes for human bone disorders." (PMID 19284518, 2009). "LRP5 and LRP6 are coreceptors for the Wnt/β-catenin pathway, and mutations in these genes can lead to altered bone mass and increased susceptibility to bone disorders." (PMID 39371752, 2024). "Our data suggested novel therapeutic discoveries targeting LRP5 in the treatment of bone disorders and metabolic diseases." (PMID 34796178, 2021). "Notably, three patients had VUS in COL1A1, LRP5, and COL1A2 that matched their suspected monogenic bone disorders." (PMID 37076969, 2023).
metabolic disorders (5 papers, 2012 to 2025). "LRP5 participates in lipid and glucose metabolism, and genetic polymorphism of LRP5 has been identified as contributing factor for metabolic disorders, which are determinants of cardiovascular disease and also closely associated with NAFLD." (PMID 35733105, 2022). "Pharmacological activation of LRP5 in adipose tissue may offer a promising strategy to prevent age-related fat redistribution and metabolic disorders." (PMID 40000740, 2025). "Our findings suggest that activating LRP5 in WAT could be a promising strategy to prevent age-related lower-body fat loss and associated metabolic disorders." (PMID 40000740, 2025).
infection (4 papers, 2013 to 2023). The state of being infected such as from the introduction of a foreign agent such as serum, vaccine, antigenic substance or organism. "Between 7 and 14 days of infection, nociceptor-ablated mice showed greater upregulation of Dbp and Bmp7, whereas control mice showed greater upregulation of Lrp5." (PMID 37845223, 2023). "E. chaffeensis was found to very strongly colocalize with the Wnt pathway coreceptor LRP5, and infection was significantly reduced in LRP5 and LRP6 RNA-silenced cells." (PMID 33883266, 2021). "LRP5 as a coreceptor for E. chaffeensis may explain how the bacterium both hijacks the signaling pathway during entry to attach to the host cell and primes it for infection by activating Wnt pathways." (PMID 33883266, 2021). "Quantitative real-time RT-PCR (qRT-PCR) analysis was used to measure the mRNA expression levels of β-catenin, cyclin D1, Dvl, LRP5, or matrix metalloproteinase-7 (MMP7) after infection with RVFV MP12 or RVFV MP12-GFP (MOI of 1) or treatment with Wnt3A in A549 cells." (PMID 27226375, 2016).